HIF1A (hypoxia inducible factor 1 subunit alpha)
Diseases named in the same sentence as HIF1A in open-access papers (continued):
Sharing a sentence is not in itself a finding about the gene and the disease.
glioma (continued). "KCN-1, a benzopyran analog, suppresses HIF-1 activity by disrupting the interaction of HIF-1α with the transcriptional coactivator p300 in glioma cells." (PMID 33235318, 2020). "Preclinical studies inducing HIF-2α knockdown reduced only in vitro glioma stem cell-mediated angiogenesis and increased glioma cell apoptosis, whereas HIF-1α knockdown resulted in reduced cell growth in both stem cells and non-stem cells." (PMID 32326644, 2020). "As hypoxia worsens, hypoxia-induced glioma-derived exosomal miRNA-199a-3p can be upregulated by the activation of HIF-1α and is able to increase the ischemic injury of neurons by inhibiting the mTOR pathway." (PMID 33110474, 2020). "Alternatively, miR-124-3p expression was significantly increased in HIF1A knockdown hypoxia-treated glioma cells." (PMID 32127518, 2020). "Glioma cells with the enhanced nuclear accumulation of HIF-1α, which we have reported as a phenotype of quiescent stem-like glioma cells, were predominantly localized in the peri-necrotic niche in which cells were negative for GINS components." (PMID 30465075, 2019). "A study using mice with Treg cell-specific deletion of HIF-1α has revealed that, under hypoxia in a mouse model of glioma, HIF-1α directs glucose away from the mitochondria, leaving Treg cells dependent on fatty acids for mitochondrial metabolism." (PMID 31921097, 2019). "The IDH1/2 mutations can produce a high level of 2-HG to inhibit the differentiation of glioma stem cells, upregulate the formation of the tumor microenvironment, and produce a high level of HIF-1α to promote the invasion of glioma." (PMID 31263678, 2019). "With immunohistochemistry, 35 frozen glioma tissues from the 180 cases were separated into a high HIF1α-expression group (IHC score: 0–6) and a low-expression group (IHC score: 7–12)." (PMID 30988674, 2019). "As expected, HIF-1α expression in C6 glioma was decreased in response to ISL treatment as compared with the control." (PMID 31438982, 2019). "Findings from this study suggest that, in combination with IR, targeting Hif-1α through its MAPK-mediated stabilization possibly has the potential to increase the efficacy of IR treatment in glioma." (PMID 31632280, 2019). "We also used a classic HRE-luciferase vector to monitor the transcriptional activity of HIF1α when pcDNA3.1-ANKDD1A or pCDNA3.1-FIH1 was transfected in glioma cells under hypoxia." (PMID 30082910, 2019). "In gliomas, there seems to be a positive correlation between HIF-1α and DCE perfusion parameters, and other studies an inverse correlation has been reported." (PMID 31437208, 2019). "Whereas, we found a significant decrease of BNIP3L/NIX and HIF-1α in C6-glioma and N2a cells after treatment with Cur and or SLCP, whereas no significant changes were observed in the case of FUNDC1 protein in both the cell lines." (PMID 30669284, 2019). "Overexpression of HIF1α in surgically resected glioma tissues has been found to have a positive correlation with invasiveness and poor survival." (PMID 30988674, 2019). "Glioma EV mediated transfer of HIF-1α promotes invasive capacity along with inducing radioresistance in sensitive glioma cells." (PMID 32038644, 2019). "Glioma tissues with overexpressed HIF1α showed high levels of circDENND2A and low levels of miR-625-5p." (PMID 30988674, 2019). "Accumulated research have shown the importance role of HIF-1α/VEGF in the regulation of glioma angiogenesis." (PMID 31681604, 2019). "Hypoxia also provides a niche microenvironment that maintains glioma stem-like cells (GSCs), a phenomenon in which HIF-1α plays a critical role." (PMID 31530290, 2019). "The U-87MG/Luc and U-138MG/Luc glioma cells over-expressing HIF-1α or knockdown ELTD1 were injected into the animal brain parenchyma (n = 5)." (PMID 31554859, 2019). "For example, knock-down of HIF-1α in glioma cells significantly impairs their migration in vitro, as well as their ability to invade into the brain parenchyma in vivo." (PMID 30669284, 2019).
glioma (continued). "In glioma studies, the expression of HIF-1α has been correlated positively with tumor grade, which is a strong prognostic factor for survival in gliomas." (PMID 31437208, 2019). "In another study with gliomas, a positive correlation was observed between HIF-1α and relative cerebral blood volume, but in that study, the expression level of HIF-1α did not correlate significantly with either Ktrans or Kep values." (PMID 31437208, 2019). "Small molecule- or siRNA-mediated inhibition of HIF-1α can induce apoptosis in gliomas, sensitizing them to chemotherapeutic agents and impairing cancer cell migration and invasion in vitro under hypoxic conditions." (PMID 31530290, 2019). "The experimental results show that the expression of HIF-1α is significantly upregulated in tumor cells surrounding the necrotic area of glioma due to exposure to hypoxia, and these cells often exhibit migration patterns." (PMID 31263678, 2019). "Taken together, our results indicate that ELTD1 promotes the proliferation, migration and invasion of glioma cells by regulating HIF-1α protein expression." (PMID 31554859, 2019). "In order to test the clinical relevance of our findings, we stained by immunohistochemistry (IHC) 128 samples retrieved from 87 glioma patients for the expression of HIF-1α, TCF1, TCF4 and the neuronal marker βIII-tubulin." (PMID 31410187, 2019). "In support of this, the depletion of HIF-1α alters the proliferation of glioma-derived bCSCs through blocking the interaction of HIF-1α and NICD." (PMID 30832246, 2019). "Our study establishes a role for 2-HG, acting via HIF-1α, in the downregulation of PC and PE synthesis in IDHmut gliomas." (PMID 29619216, 2018). "By using several established glioma cell lines under a hypoxic condition mimicked by cell treatment with CoCl2, we verified HIF1A-dependent up-regulation of PDL1 in mRNA and protein levels." (PMID 30393513, 2018). "To evaluate HIF1A/PDL1 signaling axis in gliomas, we used U251 and U87 established glioma cell lines." (PMID 30393513, 2018). "Additional studies are needed to investigate mechanisms underlying HIF-1α-mediated NHE1 expression and its impact on the TMZ chemoresistance in glioma." (PMID 30262908, 2018). "Glioma-associated DEGs AKT2, CCL3, STAT2, VEGFC were up-regulated and HIF1A, KRAS, RET, TGFB2 were down-regulated specifically in the dogs." (PMID 29352201, 2018). "The contribution of HIF1A to the control of cell migration has been reported in a number of tumors including gliomas, and our findings are consistent with these observations." (PMID 30227871, 2018). "Further studies are needed to delineate the mechanism by which HIF-1α downregulates CK and EK activity in IDHmut gliomas." (PMID 29619216, 2018). "Amongst these genes, HIF1A, a molecule known to control glioma cell migration was most significantly downregulated by LSD1 inhibition." (PMID 30227871, 2018). "In contrast, HIF-1α knockdown in glioma cells inhibited cell migration in vitro and cell invasion in vivo." (PMID 29899167, 2018). "Taken together, the results demonstrate that HIF-1α is a key upstream inducer of miR-26a expression in glioma." (PMID 30425242, 2018). "The aim of this study was to investigate the role of HIF-1α activity as a biomarker of responsiveness to TMZ in a panel of glioma cell lines characterized by different MGMT methylation status and genetic background." (PMID 30013951, 2018). "To evaluate the effects of hypoxia on glioma chemo-resistance, we found significantly increased levels of HIF-1α from 6 to 48 h post hypoxia treatment 23 and hypoxia decreased glioma cells sensitivity to different doses of TMZ." (PMID 30425242, 2018). "Taken together, these results suggest that 2-HG-mediated stabilization of HIF-1α downregulates CK activity and EK activity and thus leads to reduced PC and PE levels in IDHmut glioma cells." (PMID 29619216, 2018).
glioma (continued). "Our study points to HIF-1α as the primary driver behind reduced CK and EK activity and thus PC and PE levels in IDHmut gliomas." (PMID 29619216, 2018). "The tumor hypoxia was examined by the assessment of expression of hypoxia inducible factor HIF2α, which is more specific than HIF1α for brain tissue and is widely expressed in high grade gliomas including GBM." (PMID 29662659, 2018). "The aim of this study was to identify the role of which TFF3 plays as a potential oncoprotein that influences various aspects of glioma cell maneuver via regulating HIF-1α." (PMID 29100347, 2017). "To this end, we first detected the protein level of HIF-1α in glioma tissues and normal brain tissues." (PMID 29100347, 2017). "Our data confirmed that silenced expression of HIF-1α lad to markedly suppressed PLOD2 expression in glioma cells under hypoxia." (PMID 28410212, 2017). "As expected, HIF-1α was dramatically overexpressed in high-grade glioma tissues as demonstrated by Western blotting analysis." (PMID 29100347, 2017). "The role of HIF-1α in the regulation of PLOD2 was further investigated through exposure of glioma cells to the HIF-1α inhibitor PX-478." (PMID 28423580, 2017). "Within glioma cells hypoxia upregulates serine hydroxymethyltransferase (SHMT2) due to increased HIF-1α and c-Myc activity." (PMID 28491867, 2017). "Already known to be crucial to glioma cell adaptation to hypoxia, HIF-1α promotes the long-term maintenance of glioma stem cells (GSCs) function - the cell population responsible for tumor self-renewal and chemoresistance." (PMID 29097800, 2017). "We conclude that HIF1α expresses at first in hypoxia and then promotes the dedifferentiation and vessel formation of glioma cells." (PMID 28427209, 2017). "We uncovered a potential oncogenic role for CCDC109B in glioma progression and identified HIF1α as a possible transcriptional regulator." (PMID 28754121, 2017). "Prominent PLOD2 staining was found in 74 of 125 patients with glioma while prominent HIF-1α staining was found in 76 of 125 patients." (PMID 28410212, 2017). "To further assess the contribution of miR-218 and Bmi1 on glioma development, we examined the expression levels of pAKT and HIF-1α, which belong to the PI3K pathway." (PMID 29220380, 2017). "Recently, we have reported that miR-675-5p promotes glioma growth by stabilizing HIF1α; here, by use of the syngeneic cell lines we investigated the role of the miR-675-5p in colon cancer metastasis." (PMID 28061476, 2017). "We also found that TFF3 promotes cell proliferation, cell metastasis and inhibits cell apoptosis by regulating Hypoxia-Inducible Factor -1α (HIF-1α) under normoxic conditions in glioma cell in vitro." (PMID 29100347, 2017). "Studies in glioma cell lines suggest that ID2 interference with VHL activity can deregulate HIF1α expression and promote tumorigenesis in xenograft models." (PMID 29053101, 2017). "Previous results showed that an 8-week intermittent induction of HIF-1α, whose expression was regulated by tetracycline, promoted the growth or invasion of human glioma cells in mouse brains." (PMID 28977888, 2017). "Glioma tumors were embedded in paraffin block, and subjected to co-immunofluorescence staining for HIF-1α and ICAM-1." (PMID 29228586, 2017). "We also proved significantly positive correlation of Hif-1α and H19 depending on PTEN status in human GBM, since mutation or loss of expression of PTEN is usual in glioma and occurs in about 40% of GBM24." (PMID 28327666, 2017). "The authors previously reported that IL-1β induces HIF-1α in glioma cells through an IL-1β-HIF-1α feedback loop." (PMID 28781970, 2017). "HIF-1α is highly expressed in gliomas and closely related to tumor progression, invasion and abnormal vascular development and has been an attractive target for the glioma diagnosis and therapy." (PMID 29156717, 2017).
glioma (continued). "Significant up-regulation of HIF-1α expression has been demonstrated in glioma cells and clinical specimens, and there is accumulating evidence that down-regulation of HIF-1α can inhibit tumor angiogenesis and cell invasion." (PMID 29156717, 2017). "Taken together, these results indicated that PLOD2 expression induced under hypoxia in glioma cells was mediated by HIF-1α." (PMID 28423580, 2017). "Here we report on the feasibility of inhibiting HIF-1α expression and its downstream signaling with a cardiac glycoside, digitoxin, in glioma stem cells." (PMID 28410215, 2017). "We previously showed that hypoxia promotes the preferential expansion and maintenance of CD133 positive human glioma stem cells (GSC) in a hypoxia inducible factor 1 alpha (HIF-1α)-dependent mechanism." (PMID 28410215, 2017). "In conclusion, TFF3 drives aberrant glioma cells proliferation and invasion in vivo and in vitro through a hypoxia-independent HIF-1α induction." (PMID 29100347, 2017). "In glioma cells, both HIF-1α and HIF-2α enhance glioma sphere formation and cell proliferation, induce stemness, and increase tumor initiation ability." (PMID 28740831, 2017). "Since HIF-1α is the only oxygen regulatory subunit of HIF-1 and participates in the development and progression of glioma, we focused our subsequent research on the HIF-1α subunit." (PMID 29156717, 2017). "In summary, following an analysis of our results, we conclude that HIF1α facilitates the dedifferentiation of normal glioma cells and maintains GSC stemness to promote chemoresistance." (PMID 28801626, 2017). "Accordingly, silencing DNA-PKcs expression in four human glioma cells lines reduced HIF-1α levels and increased their radiosensitivity." (PMID 29246031, 2017). "Transwell assay further showed that CCDC109B is a critical factor in mediating HIF1α-induced glioma cell migration and invasion." (PMID 28754121, 2017). "Slices of the glioma were stained with anti-E-Cadherin and anti-HIF1a antibodies and analyzed by confocal fluorescence microscopy." (PMID 29212174, 2017). "This safe antibacterial dye induces cell death and apoptosis in several glioma cell lines, targets HIF-1α–mediated pathways, and decreases the level of PGK1, VEGF and HIF-1α in vitro and in vivo." (PMID 29097800, 2017). "In contrast, an increased resistance of TMZ to glioma cells was demonstrated after HIF1α over-expression in 95%O2." (PMID 28801626, 2017). "In order to identify the function of TFF3 and HIF-1α playing in glioma, we constructed U87 and U251 TFF3-knockdown/ HIF-1α-knockdown stable cell lines." (PMID 29100347, 2017). "These experiments demonstrated that IL-1β induces HLA-G in glioma cells in a HIF-1α-dependent manner." (PMID 28781970, 2017). "Here, we show a hypoxia-independent mechanism of HIF-1α induction in glioma, in which TFF3 cooperates with HIF-1α by upregulating its expression and transcriptional activity." (PMID 29100347, 2017). "A 48 hours induction of US28 expression in synchronized U251 glioma cells similarly resulted in HIF-1α upregulation (6.7 ± 1.2 fold increase)." (PMID 27602585, 2016). "The relative densities of SDF-1α and OPN labeling were 1.3- and 2.1-fold higher, respectively, in high HIF-1α gliomas than in low HIF-1α glioma sections." (PMID 27602954, 2016). "TAMs were localized close to perivascular niches in low-HIF-1α glioma tissue and their distribution became more disseminated as HIF-1α positive regions increased." (PMID 27602954, 2016). "Both POSTN expression and TAM infiltration were concentrated in perivascular areas in low HIF-1α glioma tissues, but their distribution became more disseminated as the expression of HIF-1α increased." (PMID 27602954, 2016). "IL6 and p-STAT3 levels correlated with the abundance of autophagic cells and HIF1A levels in human glioma tissues and with the grade of human glioma, whereas inhibition of exogenous or endogenous IL6 repressed autophagy in glioblastoma cells in vitro." (PMID 27163161, 2016).
glioma (continued). "While SDF-1α and OPN were also slightly increased in perivascular areas in high-HIF-1α glioma tissue, their expression levels and areas were much smaller than those of POSTN." (PMID 27602954, 2016). "Our study now unravels a parallel crucial mechanism on how VEGF inhibition promotes glioma invasion through the induction of HIF-1α and the EMT regulator ZEB2." (PMID 27470974, 2016). "We found that the expression level and range of POSTN were each much higher and more disseminated in high-HIF-1α-expressing glioma sections than in low-HIF-1α expressing glioma specimens." (PMID 27602954, 2016). "TAMs were enriched in perivascular areas in low HIF-1α glioma sections, but their distribution became more diffuse when the HIF-1α positive area grew in size." (PMID 27602954, 2016). "Herein, we demonstrate that Lon is an HIF-1α target and plays an important role in the malignant glioma phenotype." (PMID 27764809, 2016). "Gain- and loss-of-function xenograft manipulations demonstrated that a mutant IDH1 restricts glioma aggression by reducing HIF1α-dependent TNC expression to decrease ECM stiffness and mechanosignalling." (PMID 27820599, 2016). "To investigate the connection between hypoxia and POSTN production, we performed immunofluorescence staining for POSTN and HIF-1α in sections from different grade gliomas." (PMID 27602954, 2016). "In line with a hypoxia-mediated increase in invasiveness following anti-angiogenic therapy, we found that HIF-1α was highly upregulated directly behind the invasive front in bevacizumab-treated gliomas." (PMID 27470974, 2016). "While several lines of evidence have indicated that HIF-1α mediates the hypoxia-induced promotion of stemness in glioma cells, the implication of HIF-2α in the biology of GSCs has also been demonstrated." (PMID 26799577, 2016). "TAMs are located close to perivascular niches in gliomas with low HIF-1α expression, and their distribution became more dispersed in gliomas with high HIF-1α expression." (PMID 27602954, 2016). "We found that glioma aggression and patient prognosis correlate with HIF1α levels and the stiffness of a tenascin C (TNC)-enriched ECM." (PMID 27820599, 2016). "Here, the authors show that EphrinB2 expression is reduced in glioma cells both by genetic and epigenetic alterations and under hypoxia, through a HIF1α-mediated direct regulation of ZEB2, which enhances invasion and anti-angiogenic resistance." (PMID 27470974, 2016). "We found that in low HIF-1α expressing glioma specimens, some HIF-1α expression was localized in and around the blood vessel walls in perivascular niches." (PMID 27602954, 2016). "Consistently, silencing of HIF-1α abrogated the hypoxic increase in ZEB2 protein levels, whereas overexpression of HIF-1α in normoxic human glioma cells was sufficient to increase the levels of ZEB2." (PMID 27470974, 2016). "Recurrent IDH1-mutant patient gliomas had a stiffer TNC-enriched ECM that our studies attributed to reduced miR-203 suppression of HIF1α and TNC mediated via a tension-dependent positive feedback loop." (PMID 27820599, 2016). "We observed that POSTN+ cells were located closer to perivascular niches in low HIF-1α glioma specimens." (PMID 27602954, 2016). "We propose a model of glioma progression in which hypoxia stabilizes HIF-1α protein, which in turn binds to the Lon promoter and promotes Lon expression." (PMID 27764809, 2016). "GFAP expression co-localized with HiF-1α with high levels in the glioma cells surrounding the blood vessels." (PMID 26689994, 2016). "HIF-1α expression is correlated with tumour grade in gliomas, with the highest expression found in high-grade gliomas." (PMID 26966676, 2016). "We found that in gliomas that expressed low levels of HIF-1α, 58.8% of the POSTN+ cells were CD133+ GSLCs." (PMID 27602954, 2016).